CD3E (CD3 epsilon subunit of T-cell receptor complex)
Description:
Part of the TCR-CD3 complex present on T-lymphocyte cell surface that plays an essential role in adaptive immune response. When antigen presenting cells (APCs) activate T-cell receptor (TCR), TCR-mediated signals are transmitted across the cell membrane by the CD3 chains CD3D, CD3E, CD3G and CD247/CD3Z. All CD3 chains contain immunoreceptor tyrosine-based activation motifs (ITAMs) in their cytoplasmic domain. Upon TCR engagement, these motifs become phosphorylated by Src family protein tyrosine kinases LCK and FYN, resulting in the activation of downstream signaling pathways. CD3E ITAM phosphorylation creates docking sites for the protein kinase ZAP70 leading to ZAP70 phosphorylation and its conversion into a catalytically active enzyme (By similarity). In addition of this role of signal transduction in T-cell activation, CD3E plays an essential role in correct T-cell development (By similarity). Also participates in internalization and cell surface down-regulation of TCR-CD3 complexes via endocytosis sequences present in CD3E cytosolic region. In addition to its role as a TCR coreceptor, it serves as a receptor for ITPRIPL1. Ligand recognition inhibits T-cell activation by promoting interaction with NCK1, which prevents CD3E-ZAP70 interaction and blocks the ERK-NFkB signaling cascade and calcium influx.
Synonyms: T3E; CD3epsilon; CD3-epsilon; IMD18; TCRE
Tractability: Small molecule: a structure with a bound ligand is known; it has a binding pocket of medium quality. Antibody: an approved drug acts on it; UniProt places it where antibodies can reach, with high confidence; its Gene Ontology location is reachable by antibodies, with high confidence; UniProt predicts a signal peptide or a membrane-spanning region; the Human Protein Atlas places it where antibodies can reach. PROTAC: ubiquitination databases record sites on it; its protein half-life has been measured. Other modalities: a drug acting on it is in phase 2 or 3 trials.
Target class: Membrane receptor
Gene: Protein-coding gene on chromosome 11 (118,304,730 to 118,316,175, forward strand). Ensembl gene ENSG00000198851.
Subcellular location: Cell membrane
Subcellular location (Human Protein Atlas): Endoplasmic reticulum; Plasma membrane; Golgi apparatus
Pathways (Reactome):
Immune System: Co-inhibition by PD-1; Downstream TCR signaling; Generation of second messenger molecules; Immunoregulatory interactions between a Lymphoid and a non-Lymphoid cell; Phosphorylation of CD3 and TCR zeta chains; Translocation of ZAP-70 to Immunological synapse
Gene Ontology:
Molecular function: identical protein binding; MHC class II receptor activity; protein binding; protein-macromolecule adaptor activity; SH3 domain binding; transmembrane signaling receptor activity; protein kinase binding; signaling receptor complex adaptor activity; T cell receptor binding
Biological process: negative regulation of gene expression; positive regulation of gene expression; positive regulation of T cell proliferation; T cell receptor signaling pathway; adaptive immune response; alpha-beta T cell activation; cell surface receptor protein tyrosine kinase signaling pathway; cell surface receptor signaling pathway; G protein-coupled receptor signaling pathway; gamma-delta T cell activation; positive regulation of cell-cell adhesion mediated by integrin; positive regulation of cell-matrix adhesion; positive thymic T cell selection; protein-containing complex assembly; regulation of apoptotic process; signal complex assembly; T cell activation; cerebellum development; dendrite development; regulation of signal transduction
Cellular component: alpha-beta T cell receptor complex; external side of plasma membrane; plasma membrane; T cell receptor complex; gamma-delta T cell receptor complex; cell body; cell-cell junction; dendritic spine; immunological synapse; membrane
Genetic constraint (gnomAD): Loss-of-function variants: 10 observed, 25.73 expected, observed/expected ratio (o/e) 0.39, 90% interval 0.24 to 0.66. The synonymous counts are far from expectation, so gnomAD's model fits this gene poorly and the ratio says little. Missense variants: 205 observed, 242.83 expected, observed/expected ratio (o/e) 0.84, 90% interval 0.75 to 0.95. Synonymous variants: 66 observed, 91.29 expected, observed/expected ratio (o/e) 0.72, 90% interval 0.59 to 0.89.
Gene-disease validity (ClinGen):
ClinGen rates the evidence that CD3E causes each of these diseases.
immunodeficiency 18 (autosomal recessive): Definitive. Immunodeficiency-18 is an autosomal recessive primary immunodeficiency characterized by onset in infancy or early childhood of recurrent infections.
Homologues: Orthologues: chimpanzee CD3E (99% identical), macaque CD3E (75% identical), pig CD3E (60% identical), guinea pig CD3E (60% identical), rabbit CD3E (60% identical), rat Cd3e (59% identical), mouse Cd3e (58% identical), dog CD3E (43% identical), tropical clawed frog cd3e (32% identical). Paralogues in human: CD3G (24% identical), CD3D (21% identical).
Diseases named in the same sentence as CD3E in open-access papers:
CD3E is named in the same sentence as 165 diseases in open-access papers, as found by Europe PMC text mining. Sharing a sentence is not in itself a finding about the gene and the disease. The quoted sentences say what the papers report.
melanoma (22 papers, 2016 to 2024). A malignant, usually aggressive tumor composed of atypical, neoplastic melanocytes. "From the Human Protein Atlas, it was shown that the high expression of CD3E was also associated with patients’ long-term survival in other types of cancer, such as endometrial cancer, melanoma, head and neck cancer, and breast cancer." (PMID 30445744, 2018). "Expression of CD3E (a general T cell marker) clearly demarcated a subset of major and minor clusters, representing a substantial fraction of all cells of ~50% for melanoma PBMCs and >90% for the T zone lymphoma." (PMID 38649520, 2024). "We found an association of the combined gene signature with survival when using a cox proportional hazard regression model that corrected for age, AJCC tumor stage, CD3E expression in patients with melanoma (p < 0.01)." (PMID 37620372, 2023). "Preclinical studies in melanoma-bearing syngeneic mice revealed that the concomitant blockade of CD3E and TRP-1 facilitates tumor shrinkage through the enhanced influx of innate and adaptive immune cells." (PMID 36291815, 2022). "We observed strong Pearson correlation coefficients between IL32 expression, found within the melanoma tumor and the surrounding microenvironment, and genes related to immune cell infiltration, such as CD3E (0.94), CD8A (0.89), IFNγ (0.75), and GZMB (0.86)." (PMID 30953519, 2019). "In the example of a melanoma BrM tissue section where tumor parenchyma was surrounded by inflammatory stroma (patient 16), densities of CD3E, CD4, CD8A, and CD8B transcripts were highest in the peritumoral inflammation and in the directly adjacent tumor parenchyma." (PMID 35584630, 2022). "Moreover, we analyzed the expression level of gene CD3E, CD4, CD8A, GZMB, NKG7, TCF7 and TRBC2, the well-known markers for CD8+ T cells, and they were all shown to have significantly higher expression level in melanoma patients with low risk." (PMID 34040608, 2021). "The markers utilized in the conducted study, as defined by Tirosh and colleagues, successfully differentiated between various cell types, including melanoma cell (MLANA, PMEL), T cell (CD2, CD3D, CD3E, CD4, CD8A)." (PMID 37620327, 2023). "All phenotypic and functional markers of T cells—CD3E, CD4, CD8B, FOXP3, GZMB, PRF1 and TBX21—were expressed at higher levels in melanoma patients with high ETV7 expression." (PMID 33424867, 2020). "In addition to the purity check upon cell sorting, potential CTL contamination in melanoma cell samples isolated from the co-cultures was checked by including a series of CTL markers on the NanoString (CD3D, CD3E, CD3G, CD8A and CD8B)." (PMID 27625650, 2016).
breast carcinoma (18 papers, 2018 to 2025). "Some novel drugs have been synthesized based on CD3E against breast cancer and solid tumors expressing CEA." (PMID 37031292, 2023). "A recombinant anti-CD3E nanobody effectively suppressed angiogenesis and tumor cell proliferation in a breast cancer mouse model." (PMID 33907159, 2021). "We found that SLAMF6 expression was highly correlated not only with the expression of T-cell markers (CD3E, CD8B, CD8A, and CD4) but also with upregulation of TCF7, PDCD1 encoding PD-1, GZMK, and effector-associated genes including IFNG and PRF1 in breast cancer." (PMID 38287061, 2024). "A purified anti-CD3E nanobody effectively inhibited the growth of breast cancer in vivo." (PMID 33907159, 2021). "In a compendium of four human breast cancer datasets, we show a clear association between high LDH-A and HIF-1α gene expression and poor outcome, and an inverse pattern of disease-free survival with immune-related gene expression (CD3E/CD4 and CD8A)." (PMID 30248111, 2018). "First, the effect of EVs on the cancer cell‐killing ability of activated T cells was examined using a co‐culture system with BT‐474 breast cancer cells and CD8+ T cells mediated by anti‐HER2/anti‐CD3E bispecific antibody." (PMID 39723610, 2024). "Breast cancer, lung squamous cell carcinoma, and lung adenocarcinoma showed a significantly higher LILRB4/CD3ε mRNA expression ratio in tumor samples than normal tissue samples." (PMID 33974041, 2021). "Furthermore, in patients with breast cancer, a limited bioinformatics analysis shows that patient outcome (metastases-free survival) is associated with an inverse pattern of metabolism-related (LDH-A and HIF-1α) and immune-associated (CD3E and CD8A, CD4) gene expression." (PMID 30248111, 2018).
Immunodeficiency (16 papers, 2010 to 2025). Failure of the immune system to protect the body adequately from infection, due to the absence or insufficiency of some component process or substance. "CD3E deficiencies can cause severe immunodeficiencies, demonstrating its importance in maintaining immune function." (PMID 40621499, 2025). "Several T-cell and thymus features are altered in CD3E gene KO/mutated mouse models, and gene defects have also been associated with immunodeficiency and higher DM1 susceptibility in females." (PMID 35237542, 2022). "CD3ε, encoded by the (CD3e) gene, is associated with severe immune deficiency and is frequently used as a protein target for CD3 antibodies." (PMID 35184642, 2022). "The results suggested that CD3E is more likely to participate in T cell-regulated immune deficiency as one of its important roles in the formation of the TCR." (PMID 34557404, 2021). "The associated SNPs in KLF12, rs149473200 and rs147344426, are eQTLs of CD3e molecule (CD3E), a protein coding gene which plays an essential role in T-cell development and its defects cause immunodeficiency." (PMID 33225922, 2020). "CD3E deficiency caused by homozygous mutations in the CD3E gene is associated with the T–B+NK+ phenotype of severe combined immunodeficiency (SCID)." (PMID 30718475, 2019). "Six genes related to (a) immune checkpoints (n = 2; BTLA and CD6); (b) regulatory macrophages and T cells (n = 2; CCR7 and CD3D); and (c) immune deficiencies and unfavorable prognosis (n = 2; CD3E and FCGR2B) were down-regulated post-RT compared with pre-RT (statistical p-range: <0.0001–0.0415)." (PMID 36291815, 2022). "The T cell antigen receptor epsilon subunit (CD3E) gene is located on chromosome 11q23.3, composed of nine exons, and is associated with autosomal recessive hereditary early-onset immunodeficiency 18 phenotype, which is a severe combined immunodeficiency variant." (PMID 34557404, 2021). "The complex plays an important role in coupling antigen recognition to several intracellular signal transduction pathways, so defects in CD3E can lead to immunodeficiency." (PMID 34557404, 2021). "One of the subunits of CD3, CD3ε coding by (CD3E) gene, is associated with severe immune deficiency and is frequently used as protein target of CD3 antibody." (PMID 33747959, 2021). "CD3E normally plays an important role in the formation of the TCR and participates in multiple signaling pathways in T cell-regulated immune deficiency." (PMID 34557404, 2021). "CD3e molecule (CD3E) is a member of the CD3 complex, and deficiency can lead to immune deficiency." (PMID 34218795, 2021).
lymphoma (12 papers, 2012 to 2024). A malignant (clonal) proliferation of B- lymphocytes or T- lymphocytes which involves the lymph nodes, bone marrow and/or extranodal sites. "Lymphoma cells are positive for CD3ε, CD56, cytotoxic molecules and EBV-encoded small RNA." (PMID 35158865, 2022). "Predominant expression of the B-cell marker B220 and weaker expression of the T-cell marker CD3e confirmed their B-cell origin, similar to that of the original transferred lymphoma." (PMID 38485719, 2024). "The majority of the observed tumors were lymphomas, which was confirmed by an enlarged spleen or lymph nodes containing CD3e positive cells." (PMID 32253367, 2020). "The lymphoma cells displayed a CD3ε/CD56/TIA-1/granzyme-B/Perforin-positive and CD20/CD79a/CD4/CD8-negative immunophenotype and positive for Epstein-Barr virus by EBER in situ hybridization." (PMID 24886075, 2014). "Lymphoma cells are positive for CD3ε (not surface CD3), CD56, cytotoxic molecules and EBV-encoded small RNA." (PMID 35158865, 2022). "This was the most notable gene cluster which included the genes CD3D, CD3E, and CD3G which are part of the KEGG pathway for Human T-cell Leukemia Virus type 1 (HTLV-I) infection (KEGG pathway hsa05166), and HTLV-I infections are a known risk factor for developing adult T-cell leukemia/lymphoma." (PMID 35927608, 2022). "Immunohistochemical analyses demonstrated that these lymphomas exhibited abundant expression of B-cell markers (B220 and CD20) and much weaker expression of the T-cell marker CD3e, confirming their B-cell origin." (PMID 38485719, 2024). "Lymphoma cells are typically CD2+, surface CD3−, cytoplasmic CD3ε+, CD56+, and cytotoxic molecules (perforin, granzyme, TIA1)+." (PMID 35158865, 2022). "The lymphoma cells express T-cell markers, such as cytoplasmic CD3 (CD3ε), CD2, and CD8, as well as the NK-cell marker CD56." (PMID 35783622, 2022). "Lastly, precisely how GRK2 influences the functionality of its interaction partners in lymphocytes including TCR CD3ε, MALT1, RKIP, etc., are important questions whose answers will advance our understanding of normal immune response as well as the pathogenesis of lymphoid cancers." (PMID 33546162, 2021). "The lymphoma cells express CD2 and CD3e, but usually not CD3s or other T-cell markers (CD4, CD5, and CD8)." (PMID 34702349, 2021).
Sepsis (11 papers, 2016 to 2025). Sepsis is defined as life-threatening organ dysfunction caused by a dysregulated host response to infection. "In summary, our research has identified twelve genes, including CD3E, CD40LG, LILRA5, and FCER2, as potential diagnostic markers for sepsis." (PMID 40129981, 2025). "PBMC samples were collected from 15 patients with sepsis and 15 healthy controls, and CD3E, HLA-DR and IL-2R were tested with flow cytometry." (PMID 38166628, 2024). "In the GSE65682 dataset, CD3E (AUC:0.9509), HLA-DRA (AUC:0.974), IL2RB (AUC:0.9931), ITK (AUC:0.9727) and LAT (AUC:0.9575) showed good diagnostic efficiency in distinguishing sepsis patients from healthy controls." (PMID 38166628, 2024). "The lower expression of the six hub genes (CD28, CD3D, CD4, IL7R, LCK, and CD3E) was observed in sepsis samples." (PMID 37113759, 2023). "Previous work also showed that CD3E expression was downregulated in the sepsis group, which is consistent with the findings of our study." (PMID 38124071, 2023). "Finally, CD3E down-regulation may indicate that antigen recognition may be uncoupled during sepsis in CD4+ T lymphocytes and T-cells." (PMID 27180802, 2016). "CD3E forms the T-cell receptor-CD3 complex, which couples antigen recognition to intracellular signal transduction pathways and is down-regulated in sepsis." (PMID 38166628, 2024). "Our preliminary experiment found that CD3E, IL2R and HLA-DR were significantly reduced in sepsis when compared to healthy control." (PMID 38166628, 2024). "CD4, CD8A, CD28, CD2, CD3E as T cell surface active molecules play important roles in the immune response process; among them, the roles of CD4 and CD8 T lymphocytes in sepsis have been widely recognized." (PMID 39654893, 2024). "Our findings revealed significant decreases in CD4, CD3e, IL-7R, CD5, CD247, CD2, CD40LG, ITK, and KLRB1, and significant elevations in MMP9, LCN2, and RETN in sepsis-induced ARDS compared to controls." (PMID 37822934, 2023). "As shown in these figures, the expression levels of RETN, S100A12, IL18R1, and KL were higher in the sepsis group, while that of GZMB, HLA-DPA1, CD3E, IL2RB, CD3G, and CCR3 were higher in the normal group (p < 0.05)." (PMID 38124071, 2023). "We also found that the expression level of CD3D, CD3E, CD4, CD28, IL7R, and LCK was statistically different between sepsis and normal groups, indicating their potential role in the development of sepsis." (PMID 37113759, 2023). "Our findings showed that the expression of RETN, S100A12, IL18R1, and KL was higher in the sepsis group, while the expression of GZMB, HLA-DPA1, CD3E, IL2RB, CD3G, and CCR3 was higher in the control group." (PMID 38124071, 2023). "The lower expression of the hub genes (CD3D, CD3E, CD4, CD28, IL7R and LCK) was observed in sepsis samples, which was consistent in all the six hub genes." (PMID 37113759, 2023). "The results showed the expression level of CD3D, CD3E, CD4, CD28, IL7R, and LCK was statistically different between sepsis and normal groups." (PMID 37113759, 2023). "Moreover, in the GSE137340 validation group, the levels of CD3E, CD40LG, FCER2, and P2RY10 expressions were markedly reduced in the sepsis group when contrasted with the control group (P < 0.05)." (PMID 40129981, 2025). "Additionally, five hub immune-related genes (CD3E, HLA-DRA, IL2RB, ITK and LAT) were identified from the protein–protein interaction network, and sepsis patients with higher expression of hub genes had a better prognosis." (PMID 38166628, 2024). "At the mRNA level, Cd3e levels representing T lymphocytes did not statistically differ between CLP-sepsis and sham groups, although at the latest time points after sepsis initiation, in the sham groups an increased influx of T lymphocytes was observed compared to CLP-septic mice." (PMID 39200137, 2024).
COVID-19 (10 papers, 2020 to 2025). A disease caused by infection with severe acute respiratory syndrome coronavirus 2. "Given the increased arginase-1 expression, we went on to assess whether neutrophils from patients with COVID-19 possessed T cell–suppressive function by coculturing healthy anti-CD3ε– and anti-CD28–stimulated T cells with neutrophil supernatants." (PMID 39253969, 2024). "We subsequently examined changes in methylation and expression levels of these gamma-delta T-related genes in bulk-tissue methylomes and transcriptomes, finding that almost 90% of genes had higher methylation and decreased expression levels in COVID-19 patients, such as CD3E." (PMID 35885892, 2022). "Increased expression of CD3E and a suppression of CD3ζ (CD247) was observed on MAIT and γδT cells in COVID-19 samples." (PMID 34721400, 2021). "Other highly-ranked genes included proposed prognostic factors (CXCL10, CD4, CD3E) and investigational therapeutic targets (IL1A) for COVID-19." (PMID 33339864, 2020). "Moreover, CD3e is one of the top prognostic factors for the analysis of host genetic data for SARS-CoV-2, which illustrates its prognostic value in COVID-19 development." (PMID 35184642, 2022).